INS (insulin)
Diseases named in the same sentence as INS in open-access papers (continued):
Sharing a sentence is not in itself a finding about the gene and the disease.
Hypoinsulinemia (continued). "In addition to the placental influence, the high rate of glucose in the amniotic fluid can prolonged the fetuses β-pancreatic cells stimulation, causing a pancreatic insulin depletion and hypoinsulinemia." (PMID 34381787, 2021). "Although hypoinsulinemia and enhanced insulin sensitivity have been linked with life extension in GH-related mutants and in dietarily restricted animals, a few long-lived mutants have been reported as not being insulin hypersensitive or as being insulin resistant, as have rapamycin-treated mice." (PMID 25244225, 2014). "Taken together, these data suggest that the hypoinsulinemia observed in the adult offspring of malnourished mothers might be caused by alterations in the regulation of glucose-induced insulin secretion via, in part, ANS modulation." (PMID 22967456, 2012). "Thus, it remains unclear whether the impaired OE regeneration in STZ mice was influenced by the loss of insulin signaling in the OE or by the high blood glucose levels caused by hypoinsulinemia." (PMID 33906971, 2021). "In addition, FFAR1 overexpression causes hypoinsulinemia and autophagy hyperactivation reduces insulin release in β-cells, suggesting that an additional crosstalk might be occurring between FFAR1 and autophagy, specifically in pancreatic β-cells." (PMID 30972025, 2019). "Together, the ability of Tm-CMV-KO mice to maintain normal glycemia in the presence of low insulin levels suggests that global Tmem127 loss leads to increased insulin sensitivity in vivo, and the hypoinsulinemia might contribute to the lower body mass of these mice." (PMID 31624249, 2019). "The importance of hypoinsulinemia causing neonatal diabetes and lethality in TALK-1 L114P mice was confirmed by insulin treatment which extended their lifespan." (PMID 38700926, 2024). "The aim of this study was to investigate the insulin effects on modulating of paired-pulse plasticity at glutamatergic synapses of hippocampal neurons under hypoinsulinemia model." (PMID 37025701, 2023). "To test this directly, we used the ex vivo pAktHF assay to measure fat body responses to insulin in flies with chronic hypoinsulinemia, or in control flies with normoinsulinemia." (PMID 36730473, 2023). "Here we combined the use of in vivo and ex vivo pAktHF ELISA to investigate and quantify dynamic changes of insulin signaling sensitivity resulting from hypoinsulinemia, over a timescale of days." (PMID 36730473, 2023). "Our results have shown that against the background of hypoinsulinemia, insulin has a dual action on plasticity in hippocampal synapses." (PMID 37025701, 2023). "Regarding mechanisms, our prior work revealed that hypoinsulinemia suppresses dopamine transmission in the mesolimbic reward pathway, and this effect was normalized to control levels following insulin supplementation." (PMID 38389818, 2023). "Here, we showed that electrical silencing of insulin-producing cells led to hypoinsulinemia and–initially–to reduced fat body pAktHF levels, as expected." (PMID 36730473, 2023). "In order to address how insulin affects paired-pulse plasticity in the model of hypoinsulinemia, we specifically probed the effects of 100 nM insulin, as this concentration produced a robust response in the previous studies." (PMID 37025701, 2023). "Our results show that animals with full organism PTEN deletion in adulthood present with very low blood glucose levels and hypoinsulinemia, with preserved pancreatic structure and in vitro insulin secretion in response to glucose." (PMID 35282439, 2022). "Catecholamines act as strong inhibitors of insulin secretion, which together with hypoglycemia results in a chronic state of fetal hypoinsulinemia." (PMID 34825243, 2021). "These animals displayed improved glucose tolerance and hypoinsulinemia with normal insulin sensitivity (tested by ITT) under HFD." (PMID 34032632, 2021).
Hypoinsulinemia (continued). "With higher implant volumes, mice had rather exhausted fasting insulin levels, possibly reflecting starting hypoinsulinemia." (PMID 32664368, 2020). "Reduced adiposity in Adi-Tet1KO mice on chow was accompanied by improved glucose tolerance, insulin sensitivity, and hypoinsulinemia." (PMID 32855402, 2020). "A main effect of peripartal hypoinsulinemia is the reduction in insulin’s antilipolytic properties, which facilitates the mobilization of nutrients from body reserves by increasing the rates of lipolysis and proteolysis." (PMID 32545739, 2020). "The plasma insulin value was decreased by 21.4% (p = 0.038) in the T2D group as compared with the control group, which evidenced the condition of hypoinsulinemia." (PMID 33103024, 2020). "Studies attempting to demonstrate that neuronal death directly ensues from hypoinsulinemia employed peripheral insulin administration to reverse cellular or structural damage induced by streptozotocin treatments in the CNS of rodents." (PMID 31787891, 2019). "These adult rat offspring also exhibit hypophagia, hypoinsulinemia, low body weight, low insulin secretion and low M3mAChR protein expression." (PMID 27561682, 2016). "The increased insulin secretion dramatically and rapidly decreases due to the overstimulation of fetal β cells which are depleted of insulin granules, resulting in fetal hypoinsulinemia." (PMID 25961055, 2015). "In the fetus, insulin is the main growth hormone and hyper- or hypoinsulinemia can lead to macrosomia or growth retardation, respectively." (PMID 25539997, 2014). "Control female mice displayed only a minor increase in blood glucose despite hypoinsulinemia and an 87% decrease in β-cell mass and pancreatic insulin concentration." (PMID 24498408, 2014). "Although epidemiology studies tend to show a positive relationship between TCDD body burdens and insulin levels, TCDD typically causes hypoinsulinemia and increased insulin sensitivity in animals." (PMID 23651634, 2013). "Fasting normoglycemia and hypoinsulinemia, glucose intolerance and low plasma glucose and insulin concentrations during an intravenous glucose tolerance test were observed in the adult offspring of malnourished mothers." (PMID 22967456, 2012). "During chronic hypoinsulinemia, neural tissues, which are insulin independent, have a competitive advantage over tissues that rely on insulin-mediated uptake, such as liver, skeletal muscle, and adipose tissue." (PMID 21773031, 2011). "The knockin mouse suffers from diminished level of pancreatic insulin, hypoinsulinemia and impaired glucose tolerance, as do S6K1−/− mice." (PMID 19479038, 2009). "Whether hyperinsulinemia or hypoinsulinemia was present, quercetin restored insulin levels to normal (normoinsulinemia)." (PMID 40806520, 2025). "Consequently, the pancreatic islet decreased its insulin secretion and the adrenal cortex activated to enhance cortisol secretion, resulting in the observed hypoinsulinemia and hypercortisolemia in the IPG and NIPG." (PMID 40266925, 2025). "Therefore, individuals with severe AN experience hypoinsulinemia, and a low level of insulin augments lipolysis and ketogenesis." (PMID 38921471, 2024). "Insulin sensitivity in target organs can adapt to changes of insulin output, and our findings suggested that insulin sensitivity in the fat body might be increased in adaptation to chronic hypoinsulinemia." (PMID 36730473, 2023). "In order to determine whether insulin affects presynaptic expression of glutamatergic plasticity at hippocampal synapses under hypoinsulinemia, the standard paired-pulse plasticity paradigm was applied." (PMID 37025701, 2023). "Therefore, insulin has an anabolic action while, on the contrary, hypoinsulinemia promotes the reverse process." (PMID 36839279, 2023). "In both subgroups, the insulin action on hippocampal neurons cultured under hypoinsulinemia conditions did not cause significant changes of their eEPSCs amplitudes (1st eEPSC in a pairs)." (PMID 37025701, 2023).
Hypoinsulinemia (continued). "In AoSHF, in contrast to AoS6 and AoS18 groups, the hypoinsulinemia may have occurred from the pancreas being unable to produce insulin probably due to structural and functional changes and decreased food intake in animals with HF." (PMID 37047174, 2023). "This suggests hypoinsulinemia consistent with lower fasting insulin in these animals." (PMID 36949050, 2023). "Since hypoinsulinemia may affect the function of many insulin-sensitive organs, the primary culture of rat hippocampal neurons can be successfully used to determine the effect of insulin on the functioning of hippocampal synapses and their plasticity." (PMID 37025701, 2023). "In T2DM, the deterioration of insulin secretion and hypoinsulinemia may develop during the progression of the disease due to treatment failure with diet or oral hypoglycemic agents and poor glycemic control." (PMID 36615728, 2022). "Moreover, with the progressive of T2DM, pancreatic β cells become decompensated and show insulin secretory defect, subsequently developing into hypoinsulinemia." (PMID 35153796, 2022). "High-dose exposure to dimethoate in vivo increased pancreas mass and reduced the number of insulin granules within β-cells, which could contribute to the hypoinsulinemia observed in vivo." (PMID 35156417, 2022). "Secondly, hypoinsulinemia reduces glucose utilization by insulin-sensitive muscle tissues." (PMID 34825243, 2021). "In addition to hypoinsulinemia, it will be important to assess the contribution of extrapancreatic tissues by sophisticated clamp studies that can help explain insulin sensitivity in the female TSC2-KOPlacenta mice." (PMID 34032632, 2021). "Finally, post‐absorptive hypoinsulinemia and improved systemic insulin sensitivity of TG mice were abolished in TGxKO mice." (PMID 32026535, 2020). "However, hypoinsulinemia also mitigates stimulating effects of insulin on the rate of glucose utilization and phagocytosis in immune cells." (PMID 32545739, 2020). "Insulin administration causes a decrease in plasma P due to increased uptake of P in insulin-sensitive tissues; hence, the hypoinsulinemia during fasting might also lead to leak of intracellular P and thereby to increased levels of plasma P." (PMID 31236663, 2019). "However, the principal cause of DM in the affected rats of the DEK strain seems to be hypoinsulinemia, because all affected males examined showed markedly low plasma insulin levels and a decrease in pancreatic β cells." (PMID 31467929, 2019). "The idea that the perinatal inhibition of insulin secretion can program adult offspring to develop hypoinsulinemia is reinforced by the fact that islets isolated from those animals responded poorly to glucose and ACh, which can be caused, at least partially, by vagal hypotonia." (PMID 27561682, 2016). "Furthermore, the improved insulin sensitivity in obese M4K4 iKO mice was abrogated by high exogenous insulin over the course of a euglycemic clamp study, indicating that hypoinsulinemia promotes insulin sensitivity in chronically obese M4K4 iKO mice." (PMID 27226575, 2016). "Moreover, rpS6P-/- mice have diminished levels of pancreatic insulin, hypoinsulinemia, impaired glucose tolerance, reduced muscle energy content, compromised compensatory renal hypertrophy and impaired parathyroid hormone secretion after experimental uremia." (PMID 26919188, 2016). "Consistently, mice deficient of S6K1 display glucose intolerance, hypoinsulinemia and reduced β-cell size, whereas mice over expressing a constitutively active form of S6K in β-cells display increased insulin secretion in the absence of changes in β-cell mass." (PMID 26919188, 2016). "Since hypoinsulinemia promotes insulin sensitivity and vice versa, it could be debated which of these characteristics is primary and which is secondary." (PMID 23248643, 2012). "In addition, conditional expression of the inhibitory Smad7 in β-cells resulted in reduced pancreatic insulin levels and in hypoinsulinemia." (PMID 22359515, 2012).
Hypoinsulinemia (continued). "This, coupled with enhanced sensitivity to insulin in skeletal muscle due to chronic hypoinsulinemia, may increase propensity for glucose to be stored as fat during “catch-up” growth and predispose offspring to childhood obesity." (PMID 21773031, 2011). "Based on the recent reports showing that insulin increases leptin translation, hypoinsulinemia may affect the leptin turnover, which might contribute in part to the metabolic phenotypes in the KRAP−/− mice." (PMID 19156225, 2009). "Therefore, we may predict the multidirectional effect of insulin on the short-term plasticity in hippocampal synapses under hypoinsulinemia depending on the baseline probability of glutamate release in them." (PMID 37025701, 2023). "Accordingly, HFD-fed Tmem135TG mice exhibited a marked improvement in glucose tolerance in the context of hypoinsulinemia and increased circulating adiponectin levels, suggesting that TMEM135 promotes insulin sensitivity." (PMID 37773161, 2023). "This revealed increased insulin sensitivity in fat body of flies with prolonged IPC silencing and insulin reduction, providing evidence of enhanced insulin sensitivity from chronic hypoinsulinemia." (PMID 36730473, 2023). "Serum insulin levels were decreased in HFD-fed KO mice, and a fasting-refeeding challenge revealed hypoinsulinemia with an increased proinsulin/insulin ratio." (PMID 31184304, 2019). "Furthermore, α cell ablation in pregnant mice impaired glucose-stimulated insulin secretion (GSIS), resulting in hypoinsulinemia and consequent disruptions in maternal glucose metabolism." (PMID 40691142, 2025). "Portal hypoinsulinemia is present when the portal system is bypassed in subcutaneous insulin administration, as opposed to the pancreas-secreted insulin." (PMID 36618347, 2022). "Plasma insulin data were more variable but generally point to hypoinsulinemia or no change in plasma insulin levels in chow-fed males." (PMID 35156417, 2022). "Similarly, SGA neonates had hypoinsulinemia in cord blood at birth compared with AGA neonates, whereas insulin levels in LGA infants were significantly higher." (PMID 34956083, 2021). "Chronic supplementation of leucine and resistance training did not reverse hypoinsulinemia in diabetic animals, but it was able to improve the concentration of serum insulin in these animals." (PMID 28536139, 2017). "The hypoinsulinemia in these mice is possibly due to increased insulin clearance, as indicated by elevated C-peptide levels and normal pancreatic insulin levels indicating normal pancreatic function." (PMID 23308073, 2012). "Hyperglycemic rats displayed progressive hypoinsulinemia, with depletion of insulin levels at 8 weeks but not at 2 weeks post-STZ." (PMID 21831292, 2011). "While the fetus at high altitude does not face hypoxia, IGFBP-1 is normally inhibited by insulin, and so the hypoinsulinemia that the fetus faces at high altitude may allow the IGFBP-1 level to rise and induce FGR in a similar manner." (PMID 38694168, 2024). "Thus, in hypoinsulinemia, we observed both PPF and PPD, which may indicate the heterogeneity of hippocampal synapses in their resistance to insulin deprivation." (PMID 37025701, 2023). "Furthermore, hypoinsulinemia in the NASH-STZ hamster could likely have increased peripheral lipolysis due to the lack of insulin-mediated lipase inhibition, which in turn results in increased flux of FFA to the liver." (PMID 33596938, 2021). "Whereas octreotide-induced hypoinsulinemia could contribute to the increased breakpoint in the PRT study and enhanced food reward (35, –, 37), increases in hedonic-brain responses to food in the fMRI study were still seen despite its prevention by coadministration of exogenous insulin." (PMID 26580235, 2016). "Hypoinsulinemia favors glucose uptake in both immune cells and MEC because these cells are not dependent on insulin whereas glucose uptake to insulin-dependent cells like adipose and muscle cells is reduced." (PMID 32545739, 2020).
Hypokalemia (185 papers, 2008 to 2026). An abnormally decreased potassium concentration in the blood. "Hypothermia therapy and insulin therapy can also cause hypokalemia due to intracellular potassium shifts." (PMID 40630352, 2025). "Concomitantly, RAAS overactivation increases renal excretion of potassium, predisposing to hypokalemia, which further impairs insulin secretion and worsens glucose intolerance." (PMID 40136609, 2025). "A decision tree model was also developed to predict the risk of post-continuous insulin infusion (CII) hypokalemia." (PMID 40546498, 2025). "The administration of insulin in this setting drives K+ back into cells, potentially causing severe hypokalemia, particularly in patients with initial normal or low potassium levels." (PMID 41149081, 2025). ",25, 26, 27, 28 Research suggests that the use of lower doses of insulin leads to a lower risk of developing hypokalemia." (PMID 40037551, 2025). "Second, rapid shifts in blood glucose and insulin concentrations can disrupt electrolyte homeostasis, particularly causing acute hypokalemia as insulin-stimulated cellular glucose uptake is accompanied by potassium influx into cells." (PMID 41463929, 2025). "The marked potassium requirements in this case support the preservation of insulin action at the cell surface level, acting upon the Na+/K+ ATPase pump to cause hypokalemia." (PMID 39588551, 2024). "Insulin induces an intracellular potassium shift by stimulating the intrinsic activity or membrane insertion of Na+-K+ ATPase, causing hypokalaemia." (PMID 39400601, 2024). "Chronic hypomagnesemia and hypokalemia, hallmark traits of GS patients, can disrupt glucose metabolism by affecting insulin secretion and sensitivity." (PMID 38333726, 2023). "Clinical cases have provided evidence that aggressively supplementing potassium in response to initial hypokalemia during the early stages of an insulin overdose can lead to hyperkalemia once the underlying cause of the insulin overdose is resolved." (PMID 38250973, 2023). "In conclusion, we discovered that abnormal glucose metabolism was common in 17OHD patients, hypokalaemia was linked to insulin secretion, and high progesterone was associated with abnormal glucose metabolism in these patients." (PMID 35937831, 2022). "Given that iron overload is associated with T2DM, this relationship is plausible since hypokalemia is associated with an increased risk for T2DM due to reduced insulin sensitivity." (PMID 34940629, 2021). "Chronic hypomagnesemia and hypokalemia are typical clinical features in GS patients and both can cause abnormal glucose metabolism secondary to impaired insulin secretion and insulin sensitivity." (PMID 34348722, 2021). "In diabetics, excessive use of insulin is associated with hypokalemia; those with low blood glucose and hypokalemia should avoid using insulin." (PMID 33152003, 2020). "The initiation of insulin causes an intracellular shift of potassium and lowers the potassium concentration potentially resulting in severe hypokalaemia." (PMID 28659865, 2017). "The steroid hormone-like effects of GA and glycyrrhetinic acid also cause some side effects, such as insulin resistance, glucose metabolism disturbance, electrolyte imbalance (hypernatremia and hypokalemia), edema, and weight gain." (PMID 28133479, 2017). "The insulin tolerance test used by Ross, mimicking a severe stress, has been abandoned due to the risk of hypoglycemic seizures and severe hypokalemia after treatment with glucose infusion." (PMID 26696958, 2015). "Insulin overdose is associated with multiple side effects including neurological damage, electrolyte abnormalities (hypokalemia, hypomagnesaemia, and hypophosphatemia), severe hypoglycaemic episodes, and liver enzyme derangement." (PMID 22924049, 2012). "Thiazides cause hypokalemia that decreases insulin secretion and receptor sensitivity insulin.[1213] Watch for diabetic control when thiazides are given together with any antidiabetic." (PMID 21042492, 2010).